HIF1A (hypoxia inducible factor 1 subunit alpha)
Diseases named in the same sentence as HIF1A in open-access papers (continued):
Sharing a sentence is not in itself a finding about the gene and the disease.
lung carcinoma (continued). "Previous data have showed that EZH2 regulates immune escape of lung cancer through HIF1A." (PMID 34838012, 2021). "In a lung cancer model, miR-18a-5p overexpression led to enhanced radiosensitivity in both the total cancer cell population and CD133+ CSC-like cells; the radiosensitizing action was associated with downregulating ATM and HIF-1α expressions." (PMID 33806538, 2021). "Widely investigated, the up-regulated HIF-1α exhibits in lung cancer." (PMID 34044859, 2021). "In addition, we also isolated CAFs and NFs from lung cancer tissues and normal lung tissues, revealing that the expression of HIF‐1α was highly expressed in CAFs." (PMID 33943003, 2021). "Moreover, it was noticed that AK4 exaggerates HIF-1α protein expression under hypoxia, leading to endothelial to mesenchymal transition in lung cancer." (PMID 34440794, 2021). "As a consequence of increased HIF-1α signaling, PD-L1 expression on lung cancer cells increases." (PMID 35070990, 2021). "Therefore, Hsp90 inhibition will be particularly relevant in HIF-1α and/or Gal3-high tumors, a biomarker context that is most frequently found in pancreatic and lung cancers." (PMID 33672199, 2021). "Moreover, miR101 expression was lower in the lung tumors and blood from the patients with lung cancer with higher HIF1α expression." (PMID 34362882, 2021). "Regarding to the functional roles of miR-449a, KDM3A and HIF-1α in lung cancer, this research was initiated to decode whether their integrity involved in lung cancer and targeting miR-449a/KDM3A/HIF-1α axis regulated cancer progression." (PMID 34044859, 2021). "Similarly, the inhibition of HSP90 activity by deguelin led to the suppression of HIF-1α in radioresistant lung cancer (H1299 and H226B) cells." (PMID 33401572, 2021). "It functions as an oncogene through silencing many tumor suppressor genes such as PDCD4, PTEN, SMAD7, HIF-1α, and others, all of which play key roles in different aspects of lung cancer development including cell cycle, apoptosis, drug resistance, and distant metastasis." (PMID 34885115, 2021). "Moreover, ABZ inhibits the migration capability of pancreatic cancer cells and HIF-1α-dependent glycolysis in lung cancer cells." (PMID 34966427, 2021). "Nicotine likely promotes lung cancer cell proliferation by upregulating HIF-1α and SOCC components." (PMID 33505535, 2021). "Third, using the GEPIA database, we identified that HIF-1α might function as an oncogene in a cancer type-specific manner; high HIF-1α expression may influence survival in lung cancer patients." (PMID 33154192, 2020). "Thus, HB-EGF drives arsenic-induced carcinogenesis, tumor growth, and lung cancer development via the EGFR/PKM2/HIF-1α pathway." (PMID 32695675, 2020). "Incomplete RFA could accelerate angiogenesis and proliferation of residual lung carcinomas through HSP70/HIF-1α." (PMID 32670888, 2020). "HIF-1α is usually expressed in tumor cells in lung cancer tissues." (PMID 32872195, 2020). "For instance, HIF-1α was reported as a prognostic factor for lung cancer patients." (PMID 32599967, 2020). "Influenza virus infection was also able to induce HIF-1α activation in lung carcinoma and monocytic cell lines; however, a lack of lung epithelial cell expression of HIF-1α in a mouse model of influenza infection was associated with enhanced virus replication." (PMID 32993138, 2020). "Although, H2S has been shown to inhibit EMT in lung cancers through Wnt/Catenin signaling and the activation of HIF-1α, HIF-1α is dramatically downregulated by gestational CS in the 7-days old mouse lung and, in some lung injuries, H2S promotes EMT and lung repair." (PMID 32849552, 2020). "The partial increase in the cell migration of HIF-1α-expressing cells under hypoxic conditions imply that additional targets may be involved in the inhibition of cell migration by miR-200c in lung cancer cells." (PMID 31061665, 2019).
lung carcinoma (continued). "It has been shown that hypoxia-inducible factor 1α (HIF1α) can be activated by the stimulation of hypoxia and also by the stimulation of nicotine in lung cancer, suggesting HIF1α is expressed by the stimulation of both hypoxia and xenobiotic toxicity nicotine in middle stage LSCC." (PMID 31217907, 2019). "Importantly, the interplay of RASSF1A-HIF-1α signaling regulates the glycolytic phenotype in these primary lung cancer cells, further supporting a broad role of RASSF1A as a hypoxia regulated protein and a crucial regulator of HIF-1α signaling." (PMID 31086178, 2019). "We thought that a similar phenomenon could happen in the interaction between miR-200c and the 3′-UTR of HIF-1α in lung cancer cells." (PMID 31061665, 2019). "Interestingly, the GSEA results showed that gene sets categorized as hypoxia response, HIF1A target, glucose metabolism, and lung cancer prognostic genes were significantly enriched in the AK4 metabolic gene signature." (PMID 30696468, 2019). "Additional studies are necessary to determine whether 1) these genes are direct targets of miR-200c; 2) their transcriptional induction under hypoxia depends on HIF-1α; and 3) they play a role in cell migration under hypoxia in lung cancer cells." (PMID 31061665, 2019). "Therefore, additional studies are necessary to identify how miR-200c exerts its effect on HIF-1α mRNA in lung cancer cells." (PMID 31061665, 2019). "Taken together, our results suggest that AK4 may serve as a critical factor dictating the prognostic power of HIF-1α in lung cancer patients." (PMID 30696468, 2019). "Overexpression of AK4 shifts metabolism toward aerobic glycolysis and increases the levels of intracellular reactive oxygen species (ROS), which subsequently stabilizes HIF-1α protein and promotes epithelial-to-mesenchymal transition (EMT) in lung cancer cells in a HIF-1α-dependent manner." (PMID 30696468, 2019). "In conclusion, our meta-analysis showed that SUVmax may predict microvessel density and expression of VEGF, KI 67, and HIF-1α in lung cancer." (PMID 29983647, 2018). "MAC significantly increased HIF‐1α expression in nuclear extracts of the three lung cancer cells." (PMID 30338933, 2018). "As miR‐18a‐5p inhibited both ATM and HIF‐1α in the present study, miR‐18‐5p could be a promising target to improve radiosensitivity in lung cancer." (PMID 29860718, 2018). "However, Lee and colleagues showed that deguelin suppressed the growth of human lung cancer cells by down-regulation of HIF1α-mediated VEGFA expression in both normoxia and hypoxia conditions." (PMID 29416603, 2018). "HIF-1α has been proven to contribute to poor prognosis and to play a critical role in tumor metastasis and angiogenesis in many types of solid tumors, including renal cell carcinoma and lung cancer." (PMID 28558056, 2017). "Moreover, a number of studies have confirmed that the nuclear expression of HIF-1α is correlated with poor prognosis in various cancers, including cervical cancer, endometrial carcinoma, and lung cancer." (PMID 28558056, 2017). "Thus, we conclude that cisplatin-resistance of lung cancer cells in hypoxic micro-environment is mostly regulated by HIF1α and the combination therapy overcomes this resistance." (PMID 27708247, 2016). "First, the model leading to this prediction is based on experimentally validated target gene-miRNA interactions as reported in miRTarBase, so that known HIF1A regulating miRNAs are apparently overexpressed in lung cancer tissue, suggesting subsequent downregulation of HIF1A, which is not the case." (PMID 27588394, 2016). "Therefore, to uncover the molecular mechanisms of lung cancer recurrence following hyperthermia treatment, the present study explores the effects of hyperthermia on HIF-1a expression and cell proliferation and angiogenesis." (PMID 27456341, 2016). "In addition, our finding indicated that Daxx gene expression in hypoxic lung cancer cells is suppressed via a novel HIF-1α-mediated mechanism." (PMID 28004751, 2016).
lung carcinoma (continued). "Furthermore, HIF-1α protein repression was more prominent in miR-622-transfected A549 lung cancer cells compared with control." (PMID 26528854, 2015). "Because we found that miR-622 plays a critical upstream mediator role in regulating lung cancer invasion and migration and repressing HIF-1α expression in vitro, we explored whether miR-622-associated metastatic suppression occurs in vivo." (PMID 26528854, 2015). "In addition, miRNA-mediated HIF1α knockdown reduces survivin expression and induces cell death, while survivin overexpression prevents apoptosis in A549 lung cancer cells." (PMID 26584646, 2015). "To examine whether miR-622 downregulates the HIF-1α axis with consequent effects on tumor metastasis, we established a xenograft model of human lung cancer cells in nude mice." (PMID 26528854, 2015). "We therefore hypothesized that lung cancer cell aggressiveness could be rescued by upregulating EGF/AKT/ERK signaling to compensate for the miR-622-mediated downregulation of HIF-1α." (PMID 26528854, 2015). "As a tumorigenesis factor, HIF-1α could induce angiogenesis of lung cancer when activated in hypoxia." (PMID 24959290, 2014). "HIF-1α affects the sensitivity of paclitaxel in lung cancer cells and targeted inhibition of HIF-1α may overcome the drug resistance of paclitaxel." (PMID 24765145, 2014). "The benefits of elucidating the HIF-1α pathway in tumorigenesis may lead to development of novel approaches for the prevention of tumor progression and for lung cancer therapies." (PMID 23732337, 2013). "Furthermore, hypoxia induced CD133 expression in human lung cancer cells by upregulation of Oct3/4 and Sox2 through HIF-1α and HIF-2α." (PMID 23840432, 2013). "Finally, we confirmed that silencing HIF-1α expression downregulates survivin expression in lung cancer xenografts." (PMID 23732337, 2013). "Our results also provide a basis to target the HIF-1α pathway in lung cancer therapy." (PMID 23732337, 2013). "Therefore, we have analyzed the effects of NVP-AUY922 and 17-AAG on the HIF-1α/HIF-2α expression in combination with radiosensitivity in lung cancer cell lines under normoxic and hypoxic conditions." (PMID 22347438, 2012). "Since hypoxia is known to modulate tumour IR responses and ATM activity, we examined the levels of the endothelial protein CD31, as a marker of microvasculature density, and those of HIF1α, as marker of hypoxia, in control and irradiated xenografts from both lung cancer A549 and H1299 xenografts." (PMID 22607554, 2012). "Moreover, siRNA mediated knockdown of FH has been shown to increase HIF-1α levels in A549 lung carcinoma cells which express VHL." (PMID 21695080, 2011). "However, we found a significant increase in HIF1α protein expressions in hypoxic lung and colon cancer tumors, but the tumor progression of lung cancer was repressed." (PMID 21812995, 2011). "We found that HIF-1α and survivin were widely expressed in both A549 cells and fresh NSCLC tissue samples and that HIF-1α expression was consistently associated with high levels of survivin expression in the lung cancer samples." (PMID 19245702, 2009). "In order to investigate if there are similar transcriptional regulation mechanisms in lung cancer, we constructed two reporter constructs; one with the normal putative binding site of HIF-1α (-19 bp ~-16 bp) in the survivin core promoter and another with a mutated form of this binding site." (PMID 19245702, 2009). "In contrast to Ndrg1, HIF-1α was present in both normal and lung cancer cells at similar levels." (PMID 15341671, 2004). "An essential element in initiation of non-small cell lung carcinoma (NSCLC) is hypoxia-inducible factor 1α (HIF-1α), which is a transcription variable reacts to oxygen deprivation, or low oxygen levels in the cellular environment, a common condition in solid tumors like lung cancer." (PMID 40205002, 2025). "Furthermore, the expression of HIF-1α was increased in all stages of lung cancer." (PMID 38880883, 2024).
lung carcinoma (continued). "Interestingly in our analysis, high HIF-1α expression was instead a protective factor of early-stage lung cancer, and this may require sufficient and detailed data for further analysis." (PMID 38609977, 2024). "Upregulation of HIF-1α in hypoxic conditions promotes increases in pro-angiogenic factors, namely, vascular endothelial growth factor (VEGF), known to be overexpressed in many lung cancers, causing an increase in tumour endothelial cell and tumour cell proliferation and angiogenesis." (PMID 39376603, 2024). "However, to determine whether the HIF‐1A‐induced downregulation of CCL2 expression is mediated through miR‐210‐3p, we analyzed mir‐210‐3p expression in HIF‐1A silenced and overexpressed A549 lung cancer cells." (PMID 35658112, 2024). "Additionally, they provide new insights into a strategy for precise targeted treatment by suggesting that HIF-1α inhibitors may serve as therapy for lung cancer patients with PDLIM2 downregulation." (PMID 38880883, 2024). "However, whether the common volatile anesthetic, sevoflurane, suppresses A549 lung cancer cell proliferation by regulating apoptosis and inhibiting HIF-1α remains a subject of debate." (PMID 36984614, 2023). "Both endogenous and exogenous H2S may be involved in the inhibition of lung cancer cells by regulating mitochondrial energy metabolism, mitochondrial DNA integrity, and phosphoinositide 3-kinase/protein kinase B co-pathway hypoxia-inducible factor-1α (HIF-1α)." (PMID 36558139, 2022). "Thus, we studied whether WDR72 affected the stemness of lung cancer cells relying on the AKT/HIF-1α pathway." (PMID 36385964, 2022). "Targeting the HIF-1α/SCD1 axis in CAFs might be a promising strategy for lung cancer therapy." (PMID 36439884, 2022). "EVs from human umbilical cord mesenchymal stem cells enhance fracture healing through HIF-1α-mediated promotion of angiogenesis in a rat model of stabilized fracture, EVs from bone marrow mesenchymal stem cell promote repair of damaged endometrium, promote metastasis of lung cancer cells." (PMID 36110319, 2022). "Additionally, the upregulation of PD-L1 expression was reversed by specific HIF-1α inhibitor, which supports the hypothesis that EVs derived from intermittent hypoxic lung cancer cells upregulate PD-L1 in macrophages via HIF-1α." (PMID 34254261, 2022). "The team of Donlin Tang found that HIF-1α stabilization promoted fatty acid uptake and lipid storage, then inhibited ferroptosis through elevated lipid droplet formation in human fibrosarcoma or lung cancer cells, suggesting the role of HIF-1α may vary as cell background." (PMID 36209275, 2022). "Moreover, HIF‐1α‐modulated ALDOA upregulated expression in lung cancer cells." (PMID 35615976, 2022). "For instance, high CD73 expression in lung cancer cells is directly linked with hypoxia-inducible factor HIF1α expression by cancer cells 28; in fulminant acute liver failure 29, CD73 expression can be increased by HIF1α; in gastric cancer, CD73 expression correlates closely with HIF-1α expression." (PMID 34659527, 2021). "Thus, we could speculate that the higher expression of plasma HSP90α, the more lung cancer tissues with HIF-1α positivity, which may affect the expression of PD-L1, affecting the efficacy of immunotherapy." (PMID 34926266, 2021). "Thus, it could be concluded that elevating KDM3A or HIF-1α negated up-regulated miR-449a-induced suppression on cellular growth in lung cancer." (PMID 34044859, 2021). "Next, in order to confirm whether inhibition of HIF-1α by vanillic acid was specific to the cell line, we extended these experiments to different tumor cell lines, including Hep3B hepatic cancer cells and A549 human lung carcinoma cells." (PMID 30678221, 2019).
lung carcinoma (continued). "In A549 lung carcinoma cells, ROS level elevation caused by nicotine treatment resulted in the phosphorylation of Akt and ERK kinases and to the stabilization of hypoxia-inducible factor 1α (HIF-1α), whereas in HepG2 hepatocytes, nicotine treatment was shown to activate the NF-κB response element." (PMID 31197632, 2019). "SUV may predict microvessel density and expression of VEGF, KI 67, and HIF-1α in lung cancer." (PMID 29983647, 2018). "Furthermore, in a recent meta-analysis, it was suggested that HIF-1α expression may be a prognostic biomarker for lung cancer." (PMID 29983647, 2018). "Therefore, our results suggested honokiol induced autophagy in KRAS mutant lung cancer cells could be attributed to Sirt3- Hif-1α pathway." (PMID 28443025, 2017). "Moreover, higher levels of HIF-1α and glucose transporters were observed in lung cancer patient tissues following chemoradiotherapy, and heightened expression of HIF-1α, glucose transporter 1, and carbonic anhydrase IX was significantly associated with worse overall and disease-free survival." (PMID 28383481, 2017). "Therefore, we examined the effects of HIF‐1α expression on chemoresistance of lung cancer." (PMID 28028936, 2017). "In our study, we could provide new insights on HIF‐1α in lung cancer." (PMID 28028936, 2017). "Similarly, HIF1α ( dark blue node) expression is regulated by several miRNAs including miR-17-92 in lung cancer cells, miR-519c and miR-18a in breast and lung cancer cells, miR-22 in colon cancer cells, miR-199a in non-small cell lung cancers and miR-429 in human endothelial cells." (PMID 27358718, 2016). "Our xenotransplantation study of the tumorigenicity of human lung cancer cells in mice confirmed that the number of lung nodules was significantly decreased in animals that received cells overexpressing miR-622, which facilitated downregulation of HIF-1α level." (PMID 26528854, 2015). "We speculate that HIF-1α could become an important target for lung cancer therapy." (PMID 23732337, 2013). "Thus, we tested the impact of HIF-1α on survivin expression in lung cancer cells." (PMID 23732337, 2013). "Therefore, nicotine may regulate HIF-1α expression in a similar PKC-dependent manner in lung cancer cells as S1P does in ML-1 cells." (PMID 23824493, 2013). "As miR-17-92 targets hypoxia-inducible factor (HIF)-1α in lung cancer cells, enhanced miR-17-92 expression in activated T cells may promote the type-1 function of T cells at least partially through down-regulation of HIF-1α." (PMID 20167088, 2010). "In lung cancer cells, ginsenoside Rg3 inhibits ROS production, leading to NF-κB and HIF-1α-mediated downregulation of PTX3, and inhibits gemcitabine induced MDR of lung cancer cells." (PMID 40490812, 2025). "In lung cancer, ALDOA exhibits a tumor-promoting effect through the EGFR/MAPK signaling cascade and modulation of HIF-1α signaling." (PMID 39755705, 2025). "We observed that the upregulation of MIF or HIF-1α can promote the glycolysis level and cell proliferation ability of AT2 cells, but still lower than that of lung cancer cell lines." (PMID 41210694, 2025). "Panaxynol treatment also significantly inhibits the interaction between HIF-1α and Hsp90, reducing HIF-1α protein levels and VEGF mRNA levels in a dose-dependent manner, further supporting its anti-lung cancer effects." (PMID 39193331, 2024). "Overexpression of HOIP significantly enhanced HIF1α expression in normoxia and hypoxia, whereas knockout of HOIP decreased HIF1α levels in lung cancer cells." (PMID 38272870, 2024). "CPM can significantly inhibit cell viability, ROS production, intracellular pH, migration in hypoxic lung cancer cells, and angiogenesis of HUVECs under hypoxia through the inhibition of APEX1/HIF-1α interaction." (PMID 39175079, 2024). "Therefore, we also investigated whether PDLIM2 regulates the HIF-1α expression in lung cancer." (PMID 38880883, 2024).